HTT (huntingtin)
Diseases named in the same sentence as HTT in open-access papers (continued):
Sharing a sentence is not in itself a finding about the gene and the disease.
Huntington disease (continued). "Huntington’s disease (HD) is caused by mutant huntingtin protein resulting from an expanded polyglutamine cytosine-adenine-guanine (CAG) repeat sequence in the autosomal dominant gene huntingtin (HTT, 4p16.3)." (PMID 24248060, 2013). "Huntington Disease (HD) is a progressive neurological disorder, with pathological manifestations in brain areas and in periphery caused by the ubiquitous expression of mutant Huntingtin protein." (PMID 24252798, 2013). "Huntington’s disease (HD) is a dominant autosomal disorder resulting from expansion of a stretch of CAG repeats near the N-terminus of the HTT gene that encodes for the protein huntingtin." (PMID 24270512, 2013). "Huntington’s disease (HD) is one of a family of progressive genetic neurodegenerative disorders caused by the pathological expansion of a CAG repeat in the HTT disease gene that encodes the protein huntingtin (Htt)." (PMID 22848498, 2012). "It has also been proposed that blockade of striatal mTOR signalling caused by the sequestration of Rhes by mutant Huntingtin might underlie the pronounced atrophy of the striatum in Huntington disease." (PMID 23027611, 2012). "In addition, the SH3 domains of PACSIN1 bind to huntingtin protein, which is mutated in patients with Huntington disease." (PMID 24957964, 2012). "Huntingtin (Htt), the protein mutated in Huntington’s disease, acts as a scaffolding protein that facilitates interaction between dynein and kinesin motors and their cargo, and phosphorylation of Htt by Akt kinase regulates the directionality of Htt-dependent transport." (PMID 25364642, 2012). "The molecular mechanisms by which polyglutamine (polyQ)-expanded huntingtin (Htt) causes neurodegeneration in Huntington's disease (HD) remain unclear." (PMID 22649566, 2012). "Huntington’s disease (HD) is an autosomal dominant neurodegenerative disorder that is caused by the expansion of a CAG triplet repeat encoding polyQ (>36Q) within the first exon of the HTT gene." (PMID 22892315, 2012). "Huntington's disease (HD) is an autosomal-dominant neurodegenerative disorder caused by CAG repeat expansion coding for a polyglutamine (polyQ) sequence in the N-terminal region of the huntingtin protein (Htt)." (PMID 22929228, 2012). "A major hypothesis in Huntington`s Disease (HD) is that misfolding of mutant huntingtin (mhtt) protein leads to aggregation and causes neurodegeneration." (PMID 22984513, 2012). "However, psychotic schizophrenia-like symptoms have also been noted amongst Huntington's disease patients consistent with the interaction of huntingtin with proteins from other schizophrenia-associated genes such as PCM1, PDE4B and DPYSL2." (PMID 21298101, 2011). "Deletion of LAS17, VPS5, or SAC6, which are associated with endocytosis and the actin cytoskeleton, not only inhibit [PSI+] induction, but also suppress the toxicity and aggregation associated with the expanded glutamine repeats of the huntingtin protein exon 1 that causes Huntington's disease." (PMID 21625618, 2011). "Furthermore, class II deletions reduced, while class I deletions enhanced, toxicity associated with the expanded glutamine repeats of the huntingtin protein exon 1 that causes Huntington's disease." (PMID 21625618, 2011). "Huntington disease (HD) is a neurodegenerative disorder characterized by progressive motor, cognitive and psychiatric deficits caused by an expanded poly-glutamine tract in the huntingtin (HTT) protein." (PMID 21854568, 2011). "Huntington's disease (HD) is a dominantly inherited neurodegenerative disorder caused by a CAG repeat expansion in the Huntingtin gene resulting in a mutated polyglutamine tract in the huntingtin protein." (PMID 21603578, 2011). "Huntington's disease (HD) is a neurodegenerative disease caused by mutant huntingtin protein containing an expanded polyglutamine tract, which may cause abnormal protein–protein interactions such as increased association with calmodulin (CaM)." (PMID 19338577, 2010).
Huntington disease (continued). "Huntington's disease (HD) is an autosomal dominant neurological disorder caused when the CAG expansions encode the polyglutamine (polyQ) stretches at the N-terminus of the huntingtin (htt) protein." (PMID 20132560, 2010). "Huntington's disease (HD) is a genetically determined neurodegenerative disorder identified by the presence of a mutation for a long series of CAG repeats (>36 repeats) in the Huntingtin (HTT) gene." (PMID 21170307, 2010). "Huntington's disease (HD) is a neurodegenerative disorder caused by aberrant expansion of a CAG repeat tract within the coding sequence of the Huntingtin (HTT) gene, resulting in the production of a mutant protein with a toxic elongated polyglutamine (polyQ) stretch." (PMID 19997493, 2009). "Huntington's disease (HD) is an inherited progressive neurodegenerative disorder caused by a CAG repeat expansion in the ubiquitously expressed HD gene resulting in an abnormally long polyglutamine repeat in the huntingtin protein." (PMID 19956633, 2009). "Inhibition of autophagy by chemical regulators, such as bafilomycin A1 and 3-methyladenine, decreases the clearance of aggregate-prone proteins such as mutant huntingtin (that causes Huntington's disease) or mutant forms of alpha-synuclein that cause familial Parkinson's disease." (PMID 18644437, 2008). "In support of this hypothesis we previously showed that a large proportion of the physical interactors of huntingtin (the protein that when mutant causes Huntington's disease) are also genetic modifiers of huntingtin-induced neurodegeneration." (PMID 18773074, 2008). "Huntington disease (HD [MIM 143100]) is a neurodegenerative disorder caused by an expanded CAG trinucleotide repeat that lengthens a polyglutamine tract near the amino terminus of the huntingtin protein." (PMID 16959037, 2006). "This knowledge may prove to be important for understanding the mechanism by which the dominant polyglutamine expansion in huntingtin determines the loss of neurons in Huntington's disease." (PMID 16109169, 2005). "Huntington's disease (HD) is a dominantly inherited neurodegenerative disorder that is caused by CAG repeats in the HD locus that extend a polyglutamine tract in a ubiquitous HEAT domain protein called huntingtin." (PMID 16109169, 2005). "Huntington’s disease (HD) is an autosomal dominant neurodegenerative disorder classically defined by the progressive loss of medium spiny neurons (MSNs) within the striatum and cortex, resulting from an expanded polyglutamine (polyQ) tract in the huntingtin protein (mutant huntingtin mHTT)." (PMID 41596533, 2026). "Huntington disease (HD) is an autosomal dominant neurodegenerative disorder caused by CAG repeat expansions in the huntingtin gene HTT resulting in a polyglutamine tail at the N terminus." (PMID 40479062, 2025). "Interestingly, this analysis revealed that the coverage and the genotyping quality for coding RED loci were good (>20×) across all genes, with the exception of CACNA1A, ATXN2 and HTT, which cause spinocerebellar ataxia 2, spinocerebellar ataxia 6 and Huntington disease, respectively." (PMID 40004498, 2025). "Huntington disease (HD) is an incurable neurological condition, wherein the mutant huntingtin (mHTT) protein accumulates in the brain and causes the disease, mainly via a toxic gain-of-function mechanism." (PMID 39325320, 2024). "Altogether, these findings indicate that ITCs are efficient agents blocking the formation of mutant huntingtin aggregates, which are the main cause of its toxicity, and thus might have a potential in developing therapeutics for Huntington’s disease and, perhaps, other proteinopathies." (PMID 39680190, 2024).
Huntington disease (continued). "Expansion of the CAG repeat in the huntingtin (HTT) gene causes the motor disturbance, cognitive loss, and psychiatric manifestations of Huntington disease (HD), but the exact mechanism by which mutant HTT (mHTT) induces its pathological effect in the brain remains unclear." (PMID 38447791, 2024). "Although Huntington’s disease is a hereditary neurodegenerative disorder caused by preferential neuronal death in specific brain regions, in our cellular model of this disease we decided to use fibroblasts as a host for transfection with a plasmid encoding mutant huntingtin (mHtt)." (PMID 39680190, 2024). "Huntington's disease (HD) is an inherited neurodegenerative disorder caused by a trinucleotide repeat expansion in the huntingtin gene, leading to the production of a mutant huntingtin protein that causes progressive neuronal loss and dysfunction, particularly in the striatum and cortex." (PMID 39054501, 2024). "Interestingly, the two foremost biological networks of these targets center on two proteins associated with neurodegeneration: the amyloid precursor protein (APP), which is linked to Alzheimer’s disease, and Huntingtin (HTT), a genetic mutation associated with Huntington’s disease." (PMID 37569576, 2023). "Huntington disease (HD) is a monogenic neurodegenerative disease caused by a dominantly inherited CAG expansion in exon 1 of the huntingtin gene (HTT) and the resulting misfolding- and aggregate-prone mutant hungtingtin protein (mHTT)." (PMID 37304076, 2023). "Interestingly, though skeletal muscle wasting is a hallmark of Huntington’s disease, the mechanism underlying this atrophy is unknown, but is postulated to be caused by disrupted cell–cell signaling due to abnormal production of the Huntingtin protein." (PMID 37424016, 2023). "Huntington’s disease (HD) is a progressive dominantly inherited neurodegenerative disease caused by the expansion of a cytosine-adenine-guanine (CAG) trinucleotide repeat in the huntingtin gene, which encodes the mutant huntingtin protein containing an expanded polyglutamine tract." (PMID 37664244, 2023). "Interestingly, in Huntington’s disease (HD), another neurodegenerative disorder caused by the amplification of N-terminal repeats in the huntingtin protein, the IPA content in the plasma is significantly decreased and may represent an effective marker of HD." (PMID 36615808, 2022). "A CAG trinucleotide repeat mutation in the huntingtin gene results in Huntington disease (HD), with similar pathology in mice and humans caused by the derived small RNAs with the CAG repeat." (PMID 36547066, 2022). "Huntington’s disease (HD) is a neurodegenerative condition caused by the expansion of a CAG-repeat domain in exon 1 of the HTT gene that leads to the expression of mutant huntingtin (mHTT) protein with an expanded polyglutamine sequence, which ultimately causes neuronal death." (PMID 35938256, 2022). "Huntington’s Disease (HD) is an autosomal dominant progressive neurodegenerative disease caused by the expansion of a trinucleotide CAG repeat in the 5′ coding region of the Huntingtin gene, leading to the expression of an abnormal protein that gradually damages cells in the brain." (PMID 35783102, 2022). "Another example is a study on Huntington disease (HD), in which a decrease in mTOR activation associated with sequestrated Huntingtin protein (Htt) aggregates in postmortem HD brains was found." (PMID 34215725, 2021). "The length of the disease‐causing trinucleotide repeat expansion in the huntingtin gene predicted the change in the precentral gyrus (P = 0.03) and the intensity of the exercise intervention predicted hippocampal perfusion change in Huntington’s disease participants (P < 0.001)." (PMID 32566927, 2020). "As an example, Huntington disease (HD) is one of the best examples of genetic disorders caused by triplet expansion in the HTT gene." (PMID 33198123, 2020).
Huntington disease (continued). "However, in certain neurodegenerative diseases, such as Parkinson’s or Huntington’s disease, the genetic mutations, which are present in specific proteins (α-synuclein and huntingtin protein, respectively) can lead to the formation of larger oligomers and aggregates." (PMID 33233776, 2020). "Huntington’s disease (HD) is a rare autosomal dominant neurodegenerative disorder caused by an expansion of cytosine-adenine-guanine (CAG) repeats (≥ 36) in the exon 1 of the Huntingtin (HTT) gene, encoding for a stretch of polyglutamine (polyQ) in the Huntingtin protein." (PMID 31820322, 2020). "This may be an indirect effect of the mutant protein or an alteration of the interaction between the polyQ-expanded protein with components/regulators of these signaling pathways, as shown for huntingtin, the polyQ-expanded protein which causes Huntington’s disease (HD)." (PMID 32992839, 2020). "Huntington's disease (HD) is an autosomal dominant progressive neurodegenerative disease that is caused by the expansion of a trinucleotide CAG repeat in the 5′ coding region of the huntingtin gene, leading to the expression of an abnormal protein that gradually damages cells in the brain." (PMID 31015277, 2019). "Huntington’s disease is an autosomal dominant neurodegenerative disorder associated with progressive motor and cognitive impairments, and the expansion of a cysteine-adenine-guanine trinucleotide (polyglutamine) repeats in exon one of the human huntingtin gene." (PMID 30837611, 2019). "Additionally, we modelled HD in OSC and found that transfection with DNA encoding a version of an N-terminal fragment of the huntingtin protein that causes Huntington’s disease (HTT586Q138-EGFP) affected morphology, IB formation, and decreased survival of neurons in culture." (PMID 31069265, 2019). "Huntington disease (HD) is an autosomal hereditary neurodegenerative disease, which is caused by a specific mutation in the gene for the huntingtin protein." (PMID 28045968, 2017). "Huntington disease (HD) is an incurable neurodegenerative disorder caused by expansion of CAG repeats in huntingtin (HTT) gene, resulting in expanded polyglutamine tract in HTT protein." (PMID 28848389, 2017). "Huntington’s disease (HD) is a rare autosomal dominant neurodegenerative disease caused by a mutation within the Huntingtin gene that induces the expression of a toxic Huntingtin protein (HTT) responsible for the neurodegeneration processes leading to motor, behavioral and cognitive dysfunctions." (PMID 27999408, 2016). "Notably, a cross-seeding activity for α-synuclein with other aggregating proteins has already been described: α-synuclein accelerates the aggregation of tau and amyloid-β, proteins implicated in Alzheimer’s disease (AD), and huntingtin, a protein involved in Huntington’s disease." (PMID 26643113, 2015). "Huntington's disease (HD) is a fatal progressive neuro-degenerative disorder caused by an autosomal dominant mutation with expansion of more than 36 trinucleotide CAG repeats (which codes for polyglutamine) in exon 1 of the huntingtin (HTT) gene that encodes huntingtin (HTT) protein." (PMID 26540094, 2015). "Huntington’s disease (HD), affecting ∼5–10 per 100,000 people in the Western world, is a progressive neurodegenerative disease caused by a genetic mutation in the huntingtin gene, leading to the production of an expanded polyglutamine stretch in the encoded protein." (PMID 26268247, 2015). "Interestingly mutant huntingtin, which is the cause of Huntington’s disease, was also shown to reduce ψm suggesting mitochondria depolarization may be a common pathological hallmark in chronic neurodegenerative diseases." (PMID 24392030, 2013).
Huntington disease (continued). "Furthermore, PPARγ exerts a neuroprotective effect on neurodegenerative disorders including Huntington disease, which is caused by disassociation of mutant Huntingtin protein with REST in the cytoplasm and therefore enhanced nuclear translocation and aberrant accumulation of REST in nucleus." (PMID 23614038, 2013). "Huntington disease (HD) is an autosomal dominant neurodegenerative disorder caused by expansion of CAG repeats in exon 1 of the huntingtin gene." (PMID 22266953, 2011). "This study describes the distribution of HTT in the human BL amygdaloid complex in samples from patients with Huntington’s disease." (PMID 41509712, 2026). "Huntington's disease is caused by a CAG expansion in the HTT gene, leading to somatic repeat instability, alternative processing of HTT pre-mRNA, and mutant huntingtin protein production." (PMID 42186428, 2026). "FKBP5 regulates the degradation of HTT through direct physical interaction, thereby influencing the progression of Huntington’s disease (HD)." (PMID 41602154, 2026). "Huntington's disease (HD), an uncurable neurodegenerative disorder, is caused by CAG repeat expansion in the HD gene encoding mutant huntingtin protein." (PMID 41850723, 2026). "Huntington's disease (HD) is a fatal neurodegenerative disorder caused by an expanded CAG repeat in the HTT gene, producing mutant huntingtin (mHTT) that misfolds into β-sheet-rich aggregates and drives neuronal loss." (PMID 41712780, 2026). "Aggregation of misfolded mutant Huntingtin (mHTT) is a pathological characteristic in Huntington’s disease (HD), implying clearance of mHTT is a therapeutical direction for this neurodegenerative disorder." (PMID 40713750, 2025). "Huntington’s disease (HD) is a progressive, autosomal dominant neurodegenerative disorder caused by a CAG trinucleotide expansion in the Huntingtin (HTT) gene." (PMID 41383707, 2025). "A-syn brain aggregates are the main inclusions found in Parkinson’s disease brains, whereas huntingtin (Htt), ataxin-1 and ataxin-2 are the main components of Huntington disease, SCA1 and SCA2, respectively." (PMID 39974178, 2025). "Huntington’s disease (HD) is caused by CAG trinucleotide expansion on chromosome 4, leading to mutant Huntingtin production." (PMID 39891767, 2025). "Huntington’s disease (HD) is an autosomal dominant, neurodegenerative disorder caused by an abnormal CAG (cytosine–adenine–guanine) repeat expansion in the huntingtin (HTT) gene." (PMID 41153780, 2025). "Huntington’s disease is classically defined as a neurodegenerative disorder of the striatum and cerebral cortex, caused by an expanded CAG repeat in the huntingtin gene (HTT) that encodes a polyglutamine (polyQ) tract in the huntingtin protein." (PMID 41294851, 2025). "Huntington’s disease results from a CAG sequence expansion in the HTT gene, leading to a mutant huntingtin protein with toxic polyglutamine tracts, whereas ALS involves the degeneration of upper and lower motor neurons with diverse genetic underpinnings." (PMID 39996748, 2025). "In Huntington’s disease (HD), silencing of HTT or MSH3 genes mitigates mutant protein toxicity and slows disease progression." (PMID 41304744, 2025). "The newly discovered receptor CCT2, for instance, facilitates the clearance of solid mutant huntingtin aggregates, offering a promising strategy for Huntington’s disease treatment." (PMID 40564109, 2025). "The Huntingtin protein (HTT), named for its role in Huntington’s disease, has been best understood as a scaffolding protein that promotes vesicle transport by molecular motors along microtubules." (PMID 40971423, 2025). "Of those remaining, the largest number of calls with predicted expansions were the ones in DMPK (myotonic dystrophy), GLS (global developmental delay, progressive ataxia and elevated glutamine) and HTT (Huntington disease)." (PMID 40004498, 2025).